EGFR (epidermal growth factor receptor)
Diseases named in the same sentence as EGFR in open-access papers (continued):
Sharing a sentence is not in itself a finding about the gene and the disease.
glioblastoma (continued). "For example, extracellular mutations in the EGFR have been linked to glioblastoma and are often associated with EGFR overexpression." (PMID 39337496, 2024). "EGFRvIII, EGFRvII, and mis-sense mutations account for the majority seen in patients with EGFR-driven glioblastoma." (PMID 38396993, 2024). "Here, we provided data from one glioblastoma patient who presented with an EGFR G598V mutation, where dacomitinib treatment led to disease stabilization." (PMID 38548752, 2024). "The overexpression of EGFR is considered to be linked to the malignant phenotype of human glioblastoma (GBMs)." (PMID 39130630, 2024). "Liposomal VP is currently being evaluated in patients with unresectable solid pancreatic tumors or advanced pancreatic cancer (NCT03033225), and patients with recurrent high‐grade EGFR‐mutated glioblastoma (NCT04590664) in a light‐independent manner." (PMID 38445882, 2024). "TERT promoter mutation shows very high incidence in glioblastoma but its highest incidence was also detected in the G1/EGFR-amplified subgroup." (PMID 38254850, 2024). "Approximately 50% of glioblastoma tumors have amplified EGFR, which is associated with a worse prognosis." (PMID 38672566, 2024). "By contrast, primary glioblastomas are more frequently associated with mutations in the epidermal growth factor receptor (EGFR), mouse double minute 2 homolog (MDM2), and PTEN, as well as loss of heterozygosity on chromosome 10p." (PMID 39529768, 2024). "EGFR ECD variants are most common in glioblastoma, where clinical trials of EGFR TKI’s have been reported." (PMID 38548752, 2024). "Glioblastoma tumors carrying these mutations have demonstrated a dependence on EGFR, and it has been shown in vitro that tumor regression occurs upon the cessation of EGFR kinase signaling." (PMID 38396993, 2024). "In this setting, the classifications include three genetic variables (TERT promoter mutation, EGFR gene amplification, +7/−10 chromosome copy number variations) as criteria to diagnose glioblastoma (grade 4), IDH-wildtype." (PMID 38674436, 2024). "EGFR amplification: Amplification of the EGFR (epidermal growth factor receptor) gene is associated with increased tumor aggressiveness and a poorer prognosis in glioblastoma patients." (PMID 38337543, 2024). "C-E-Cad, encoded by a circular RNA circ-E-cad, is overexpressed in Glioblastoma and activates EGFR through interaction with the EGFR CR2 domain, thereby maintaining glioma stem cell tumorigenicity." (PMID 38184608, 2024). "Two glioblastoma patients with somatic EGFR G598V dimerization domain mutations show responses to dacomitinib treatment followed by within-pathway resistance mutation in one case." (PMID 38548752, 2024). "Specifically, epidermal growth factor (EGFR) dysregulation has been associated with approximately 60% of glioblastoma cases." (PMID 38539424, 2024). "In the brain, it was shown that LRIG1 inhibits EGFR expression in glioblastoma cells by causing the activation of downstream signaling pathways." (PMID 38790164, 2024). "Since EGFR mutations are present in glioblastomas, anti-EGFR therapy with chemicals and antibodies is a potential treatment option." (PMID 38789573, 2024). "Epidermal growth factor receptor (EGFR) overexpression is one of the hallmarks of glioblastoma and can be linked to rapid proliferation and tissue invasion." (PMID 39457052, 2024). "EGFR dependence has been demonstrated in studies using glioblastoma cell lines with ECD EGFR mutations." (PMID 38396993, 2024). "In our study, TERTp mutations (77% vs. 56.4%, p = 0.01) and EGFR amplification (47.9 vs. 20.5%, p = 0.01) were more frequent in primary glioblastoma in comparison with recurrent tumor samples." (PMID 39684714, 2024). "In this way, TEAM-E T cells provide a potential solution to overcome the loss of EGFR variant III observed in glioblastoma after target immunotherapies like peptide vaccination or CAR-T cells." (PMID 39134804, 2024).
glioblastoma (continued). "When there is a loss of ANXA7 serving as a tumor suppressor in glioblastoma, this yields to poor control of EGFR signaling and results in a poorer prognosis for the patient." (PMID 38639785, 2024). "EGFR, a mutationally active receptor tyrosine kinase in over 50% of glioblastoma cases, features variants like EGFRvIII, EGFRvII and missense mutations, necessitating a deep understanding of their structures and signaling pathways." (PMID 38396993, 2024). "EGFR genetic testing in the expansion cohorts revealed glioblastomas with EGFR amplification, EGFRvIII mutations, and EGFR mutations not vIII (V774M, G1793T)." (PMID 38680990, 2024). "Amplified wildtype EGFR and variant EGFR enable irregulated growth through various different growth pathways in glioblastoma." (PMID 38396993, 2024). "EGFR (epidermal growth factor receptor) expression, in turn, is upregulated in about 60% of glioblastoma cases and is associated with tumor progression and γ-radiation resistance." (PMID 39399677, 2024). "The most common EGFR mutation in glioblastomas is the EGFR variant III+ (EGFRvIII+), which contains deletions of exons two through seven, or a total of 275 amino acids, rendering it constitutively active." (PMID 38539424, 2024). "This approach helps overcome antigen loss and variability, as seen with EGFR variant III (EGFRvIII) CAR-T cells secreting BiTEs to target glioblastoma cells while activating bystander T cells, enhancing the antitumour response against heterogeneous tumours." (PMID 39450176, 2024). "CAR-T therapies targeting HER2 or EGFR variant III (EGFRvIII) have been investigated for the treatment of glioblastoma." (PMID 39240078, 2024). "Gains in chromosome 7 are also common in glioblastomas and are associated with mutations or amplification of oncogenes such as EGFR and MET." (PMID 39518074, 2024). "For example, three MGPs were predicted to affect fatty acid oxidation upon mutation of the EGFR gene, which can be easily inferred from a previous finding that EGFR is known to regulate lipid biosynthesis in glioblastoma." (PMID 38468344, 2024). "EGFRvIII is a mutant variant of the epidermal growth factor receptor (EGFR) that is frequently observed in glioblastoma, a type of brain cancer." (PMID 38732150, 2024). "One potentially exciting antigen is the epidermal growth factor receptor (EGFR) antigen, as it is frequently amplified in glioblastoma and a mutant variant is only expressed on the tumor." (PMID 39364321, 2024). "The 2021 WHO Classification of CNS Tumors indicated that EGFR gene amplification is an important hallmark of glioblastoma multiforme." (PMID 38553638, 2024). "A large majority of glioblastomas demonstrate overactivation of the EGFR pathway as a result of EGFR oncogene mutations." (PMID 38639785, 2024). "Due to EGFR gene amplification, protein overexpression, mutations or in-frame deletions, EGFR signalling is frequently altered in a number of human malignancies, including glioblastoma, brain, lung, breast and ovarian cancers." (PMID 39234399, 2024). "According to studies, EGFR, whose expression is known to increase in association with the severity of glioblastomas, is thought to be involved in a signal network within the cell that includes 122 proteins and 211 interactions." (PMID 36766769, 2023). "EGFR is frequently altered in IDH-wildtype glioblastoma, with about 60% of tumors showing EGFR amplification, mutation, rearrangement, and/or altered splicing." (PMID 38201434, 2023). "Several studies have shown the antitumor efficacy of EGFR variant III-directed CAR-T cells against glioblastoma." (PMID 37420216, 2023). "Considering the large proportion of glioblastoma patients with EGFR mutations, small molecule inhibitors targeting EGFR have been at the forefront of clinical trials." (PMID 37857607, 2023).
glioblastoma (continued). "Mutations and cases of overexpression of EGFR are especially frequently found in carcinomas and glioblastomas, tumors of epithelial and glial origin, respectively." (PMID 38201251, 2023). "About 40% of glioblastomas overexpress epidermal growth factor receptor (EGFR), particularly EGFR variant III (EGFRvIII), which results from the loss of specific exons." (PMID 37900496, 2023). "Glioblastoma neoangiogenesis resulting from changes in EGFR, PDGFR, and VEGFR expression is commonly associated with phosphatidylinositide-3-kinase (PI3K) and mitogen-activated protein kinase (MAPK) signaling pathways under ROS activation." (PMID 37107298, 2023). "The molecular landscape of multifocal glioblastomas is similar to their solitary counterparts; however, EGFR mutations, and concomitant EGFR, PTEN, and TERT promoter mutations occur at an increased incidence." (PMID 37239289, 2023). "Reference: The A289V mutation in exon 7 encodes an amino acid of the extracellular domain of the EGFR protein and has been found only in the glioblastoma, low-grade glioma, head, and neck neoplasms, being rarely described in NSCLCs." (PMID 36629526, 2023). "In glioblastoma, 25–64% of tumors express EGFRvIII and are always associated with EGFR overexpression." (PMID 38137520, 2023). "The EGFR pathway exhibits abnormal activation in approximately 30% of glioblastoma patients, and it is associated with poor prognosis and tumor invasion." (PMID 37947601, 2023). "Epidermal growth factor receptor variant III (EGFRvIII) is a constitutively-activated mutation of EGFR that contributes to the malignant progression of glioblastoma multiforme (GBM)." (PMID 37283490, 2023). "Evidence suggests that CDKN2A/B deletion is one of the characteristics of astrocytomas and that chr7 gain & chr10 loss and EGFR amplification are characteristics of glioblastomas." (PMID 37274274, 2023). "By specifically repressing the CE5B + 6B enhancer region that encompasses the known GB-associated SNP rs723527, we can lower EGFR expression levels and modulate the aggressiveness of glioblastoma cells, which become less proliferative and invasive." (PMID 37803333, 2023). "In this regard, it is known that activation of the epidermal growth factor receptor (EGFR) correlates with Cdkn2a loss in glioblastoma formation." (PMID 37063827, 2023). "EGFR amplification is associated with cancer aggressiveness and correlated with shortened overall survival in glioblastoma." (PMID 36622089, 2023). "We also noticed many co-occurring TERT mutations in EGFR fusion samples, however, this is likely due to the high representation of glioblastomas, which frequently have TERT mutations." (PMID 37168365, 2023). "Glioblastoma is thought to be a copy number disease, almost 20% of them withholding EGFR point mutations, which are sometimes associated with copy alterations or rearrangements." (PMID 37446288, 2023). "In glioblastoma, missense mutations at the level of EGFR ECD were discovered and were associated with higher expression of EGFR protein, which undergoes phosphorylation when not stimulated by ligand." (PMID 37446288, 2023). "The possibility of reverse signaling protein effects on ncRNAs can also be considered certain, such as repression of miRNA-524 by EGFR overexpression or EGFRvIII mutation in glioblastomas, thereby inhibiting the tumor-suppressor activity of this miRNA." (PMID 37626776, 2023). "Among the confirmed proteins, RET, an oncogene, is known to play a role in the development of the central and peripheral nervous system, and EGFR is one of the most frequently mutated genes in glioblastoma." (PMID 36834486, 2023).
glioblastoma (continued). "Wild-type EGFR, on the other hand, is amplified in about 80% of glioblastomas, but targeting it carries a very high risk of on-target, off-tumor toxicity to skin, lungs, and gut." (PMID 37754534, 2023). "CTCs derived from glioblastoma exhibited EGFR amplification, which was associated with aggressiveness and with the presence of EGFRvIII and increased expression of SERPINE1, TGFB1, TGFBR2, and VIM genes associated with the mesenchymal subtype." (PMID 36834933, 2023). "The structural variants of EGFR, a group of intragenic EGFR fusions which resulted from the deletion of EGFR exons, are also frequently observed in glioblastoma." (PMID 38201434, 2023). "Approximately 60% of East Asian non-small-cell lung cancers (NSCLC), 30% of breast cancers, and 40% of glioblastoma multiforme (GBM) either overexpress or bear activating mutations/in-frame deletions in EGFR or its family members." (PMID 37766136, 2023). "In glioblastoma, the amplification of the EGFR gene is the most frequent RTK mutation (approximately 40%) and is mostly observed in primary GBM." (PMID 37446288, 2023). "EGFRvIII is a common mutation of the extracellular domain of the EGFR gene with deletion of exons 2-7, present in the majority of glioblastomas with EGFR amplification." (PMID 37626776, 2023). "EGFRvIII, a deletion mutant of endogenous EGFR, frequently exhibits genetic amplification and/or mutation during glioblastoma, it is an attractive target for CAR T treatment." (PMID 36721153, 2023). "In glioblastoma, EGFR mutations and amplifications account for at least 50% of molecular alterations." (PMID 38264526, 2023). "In glioblastoma, EGFR variant III, ERBB2/HER2, and IL-13 receptor α2 (IL13Rα2) are important CAR-T cell therapy targets that have been investigated in many clinical trial studies." (PMID 37420216, 2023). "In contrast, point mutations in the extracellular region of EGFR, such as R108K, A289V/D/T, G598D, and other extracellular domain mutations, are prevalent in glioblastoma." (PMID 38201434, 2023). "In glioblastoma, these mutations are nearly always found in tandem with amplified EGFR and are autoactivating via varied mechanisms." (PMID 37857607, 2023). "AXL has been primarily studied in the context of acquired resistance, with only a few reports of elevated AXL expression driving intrinsic or early resistance to targeted therapies in glioblastoma, EGFR mutation positive NSCLC, and melanoma." (PMID 37727007, 2023). "The frequency of epidermal growth factor receptor (EGFR) mutations was low but the frequency of EGFR mutations in the kinase domain was high in isocitrate dehydrogenase‐wildtype glioblastomas (GBMs) in our cohort." (PMID 35695190, 2023). "EGFRvIII occurs most commonly and is often associated as a late event in glioblastoma, occurring after amplification of wild-type EGFR." (PMID 38201434, 2023). "Other EGFR alterations are also frequent in glioblastoma, including EGFR amplification, the EGFRvIII mutation, and altered splicing and rearrangements." (PMID 36002559, 2022). "The amplification and mutation of the epidermal growth factor receptor (EGFR) is among the most frequently found genetic aberrations in glioblastoma, which can be detected in about 40%-50% of glioblastomas." (PMID 34998092, 2022). "Genomic alterations like IDH1/2 mutation, EGFR amplification and chromosomal 1p/19q deletions have been characterized in glioblastoma pathogenesis, molecular subtyping as well as treatment response." (PMID 35183197, 2022). "One of the features of glioblastoma (GBM) is the overexpression of EGFR and its most common mutation EGFRvIII." (PMID 35890400, 2022). "RTK signaling pathway was altered in 88% of sampled glioblastomas due to one or more mutations in EGFR, NF1, and PTEN genes." (PMID 35052830, 2022). "Glioblastoma is characterized by increased EGFR expression, as well as mutations of this receptor associated with active division, migration, and adhesion of tumor cells." (PMID 36615487, 2022).
glioblastoma (continued). "Common genetic alterations that are associated with glioblastoma are EGFR amplifications, mutations in the promotor region of TERT, and a gain on chromosome 7, in addition to a loss on chromosome 10." (PMID 35955806, 2022). "to analyze the expressions of EGFR and its variant EGFR vIII on plasma exosomes of glioblastoma patients." (PMID 35757760, 2022). "In My Cancer Genomics, the presence of an EGFR-G719A mutation is cited as an inclusion criterion for glioblastoma clinical trials." (PMID 35888045, 2022). "Loss of ANXA7 function stabilizes the EGFR protein, augments EGFR transforming signaling in glioblastoma cells, and promotes tumorigenesis." (PMID 35800363, 2022). "This form of EGFR is present in 20–25% of glioblastoma patients, and in patients with EGFR amplification, those carrying the EGFRvIII mutation show a significantly shorter survival time than patients without this mutation." (PMID 35456993, 2022). "EGFR mutations appear to rarely co-segregate with amplifications of the EGFR gene in H&N cancers as is often the case in glioblastoma." (PMID 35409179, 2022). "Specifically, IDH-WT glioblastoma usually contains higher level of epidermal growth factor receptor (EGFR) amplification, TERT promoter mutation and PTEN deletion, etc.." (PMID 35135556, 2022). "Following the detection of epidermal growth factor receptor (EGFR) gene alterations (such as amplifications, mutations, and translocation) in a high percentage of glioblastomas, the attempt to develop treatment strategies targeting EGFR has been pursued." (PMID 35267650, 2022). "The gene mutation pattern of the high-CCNScore group was similar with glioblastoma, including EGFR, PTEN, and NF1 mutation frequently." (PMID 36589241, 2022). "EGFRvIII-positive glioblastoma patients were treated with Rindopepimut (a vaccination targeting the EGFR deletion mutation EGFRvIII) in addition to standard chemotherapy in 2017 randomized, double-blind, phase III trial (ClinicalTrials.gov, NCT01480479)." (PMID 36457514, 2022). "Upregulation or amplification of the EGFR gene has been linked to various malignancies, including 50 percent of primary glioblastoma cases." (PMID 36011048, 2022). "Amplification of the EGFR is one of the most frequent genetic alterations associated with glioblastoma." (PMID 35693015, 2022). "In glioblastoma cells, EGFR was implicated to be essential in NK1R-mediated MAPK activation and cell proliferation." (PMID 35013118, 2022). "Amplification of EGFRvIII, the constitutively active, truncated form of EGFR, is associated with a poor prognosis, since EGFR signaling enhances proliferation, migration, and invasion of glioblastoma cells." (PMID 35053605, 2022). "EGFR amplification and TERTp mutations typically co-occur in glioblastoma, the most common and aggressive primary brain tumor." (PMID 36130485, 2022). "A couple of novel epitopes have been identified, for example, EGFR variant III (EGFRvIII) is a tumor-specific protein present in 25–30% of newly diagnosed glioblastomas (GBMs), making it a potential option for CAR T-cell therapy." (PMID 36497465, 2022). "EGFR is frequently altered in glioblastoma: 44% presented EGFR amplification, and 23% harbor EGFR mutations." (PMID 35328644, 2022). "The most common genetic alterations present in approximately 57% of glioblastomas are mutations, alternative splicing, rearrangements, and the focal ample of EGFR." (PMID 35806478, 2022). "According to CN5S (2021), the diagnosis of IDH wild-type glioblastoma is based on the presence of EGFR amplification or TERT promoter mutation, or the combined gain of the whole chromosome 7 and the loss of whole chromosome 10 (+7/−10)." (PMID 35806478, 2022).